CDH2 (cadherin 2)
Diseases named in the same sentence as CDH2 in open-access papers (continued):
Sharing a sentence is not in itself a finding about the gene and the disease.
pancreatic cancer (129 papers, 2007 to 2025). "Indeed, cadherin-2 and cadherin-3 expressions, which are associated with malignant clinicopathological characteristics, respectively in hepatocellular carcinoma and pancreatic cancer are downregulated." (PMID 31803360, 2019). "Cadherin-11 is necessary for metastatic spread in breast and pancreatic cancers, and it is remarkable that both CDH2 and CDH11 were increased in normal epithelial cells." (PMID 38473331, 2024). "During later stages of pancreatic tumor, we also found a strong expression of specific genes related to stemness (e.g. cdh2 (N-Cadherin) and nestin), confirming the activation of EMT." (PMID 24878567, 2014). "Importantly, genetic reduction in Cdh2 in a KPC pancreatic cancer model prolonged survival by ~25%, providing in vivo evidence that targeting CDH2 can improve prognosis." (PMID 41462674, 2025). "On the adhesion arm, CDH2 expression consistently associates with aggressive behavior and reduced survival across tumor types; moreover, genetic reduction in CDH2 prolongs survival in a KPC pancreatic cancer model, underscoring its prognostic and therapeutic relevance." (PMID 41462674, 2025). "Furthermore, down-regulated mRNAs of the kallikrein peptidase family (Klk1, Klk1b3, Klk1b5) and the cholecystokinin receptor type A (CCKAR), and expression of cdh2 coding for N-cadherin as well as somatostatin discriminated pancreatic tumors from pancreatic controls." (PMID 27769070, 2016). "Part of these genes have been reported in basic studies of pancreatic cancer and are closely related to the invasion and metastasis of pancreatic cancer according to the literature, including MYC, CDH2, SNAI1, YAP1, SOX2." (PMID 35237592, 2022).
bladder cancer (83 papers, 2005 to 2025). "In our study, SCAMP2 overexpression was found to promote the EMT process, evidenced by the downregulation of the epithelial marker CDH1 and the upregulation of the mesenchymal marker CDH2, thereby enhancing cisplatin resistance in bladder cancer." (PMID 40406117, 2025). "In the CENPA knockdown cells, the epithelial marker CDH1 and cell senescence marker p21 were significantly upregulated, while the mesenchymal marker CDH2 was downregulated, while CENPA overexpression can significantly inhibit the damage of MAP30 to bladder cancer cells." (PMID 40804263, 2025). "Correlation analysis in bladder cancer samples from TCGA BLCA demonstrated a positive correlation between mRNA levels of IGF2BP3 and SNAI1 (Snail), SNAI2 (Slug), CDH2 (N-cadherin), VIM (vimentin), and MMP9, further supporting the association between IGF2BP3 and EMT-related markers." (PMID 38504159, 2024).
colon carcinoma (79 papers, 2015 to 2025). "In the YUMC-C1 and YUMC-C2 drug-resistant and metastatic colon cancer cells, respectively, metastatic genes (CDH2, KRAS, CDC42, MCPH1, SRGAP) and markers of stemness (BRACA1 and 2, CD44, KRT5, WNT4, CD29, SAL4) were markedly enhanced." (PMID 33050525, 2020). "In an MBD-seq dataset for colon tumour and liver metastasis tissue, we confirmed that CDH2 and ESR1 were hypermethylated in primary colon cancer consistent with our findings." (PMID 40241172, 2025). "CDH2 and ESR1, two of the key genes in the 5hmC metastasis signature, were significantly hypermethylated at their promoters (P < 0.0001) in colon cancer compared to normal colon." (PMID 40241172, 2025). "In colon cancer, knockdown of the neurotrophic factor BDNF suppresses the expression of the mesenchymal marker CDH2 leading to anoikis and immune resistance in tumor cells." (PMID 36291283, 2022). "Prior studies found that HMGA1 regulates mesenchymal genes in colon cancer cells, such as Vimentin (VIM), N-cadherin (CDH2), E-cadherin (CDH1), and Fibronectin (FN1)." (PMID 34572547, 2021). "A functional role of ARTN in promoting colon cancer cell oncogenicity and metastasis with CSC-like behavior and chemoresistance via p44/42 MAPK dependent expression of CDH2 was further demonstrated." (PMID 34422665, 2021). "Additionally, the expressions of SPARCL1, CP and TF differed significantly between stage IV colon cancer and normal (p < 0.05), while that of SPARCL1, CDH2, CP and SERPINA5 differed significantly between rectum adenocarcinoma and normal tissues." (PMID 34422629, 2021).
colorectal cancer (72 papers, 2012 to 2026). A primary or metastatic malignant neoplasm that affects the colon or rectum. "Intriguingly, 3 of the genes (IGF1, PIK3R1, and CDH2) of the 10 were targets of miR-221/222-3p, indicating that miR-221-3p and miR-222-3p play undeniable roles in colorectal cancer." (PMID 41602427, 2026). "Of the 10 colorectal carcinomas, two expressed CDH2 mRNA and both showed reduced, but detectable, levels of CDH1 mRNA." (PMID 23029563, 2012). "N-cadherin (also known as Cadherin2 (CDH2)) is an adhesion molecule that is frequently overexpressed in several types of cancers, including breast and colorectal cancers, and is considered to be an inducer of EMT, which serves an important function in the early invasion and metastasis of cancers." (PMID 35756646, 2022). "We performed a quantitative RT-PCR assay to analyze the mRNA expression of SNAI1 (Snail1), TWIST1 (Twist1), CDH1 (E-cadherin) and CDH2 (N-cadherin) in FFPE tissue samples of colorectal adenomas (n = 41), colorectal cancer (n = 10) and normal colon mucosa (n = 10)." (PMID 23029563, 2012).
hepatocellular carcinoma (69 papers, 2013 to 2025). A malignant tumor that arises from hepatocytes. "HBx-transfected hepatoma cells incubated with CM from HUVECs also expressed mesenchymal genes including Thy1, CDH2, TGFβR1, VIM, and CD133." (PMID 31069171, 2019). "However, CDH2 overexpression has been reported in hepatocellular carcinoma." (PMID 26011628, 2015). "Analysis of miRNA profile unveiled that miR-424-5p is one of the downregulated miRNAs in anoikis-resistant hepatocellular carcinoma cells, which display elevated EMT-related factors such as CDH2 (also known as N-cadherin)." (PMID 33435156, 2021).
glioblastoma (67 papers, 1995 to 2025). The most malignant astrocytic tumor (WHO grade IV). "The cell–cell adhesion molecule N-cadherin (CDH2, N-cad) is upregulated in ∼60–80% of adult glioblastomas and is associated with increased mortality." (PMID 38477830, 2024). "The EMT process is linked with resistance to treatment, and EMT in glioblastoma cells may be complemented by enhanced N-cadherin (CDH2) expression, correlating with adverse prognosis." (PMID 35216113, 2022). "The study aimed to determine the expression of carcinogenesis-related SLC5A8, SLC12A2, SLC12A5, CDH1, and CDH2 in adult glioblastoma U87 MG and T98G cells and the effects of 0.5 mM, 0.75 mM, and 1.5 mM doses of VPA." (PMID 39061990, 2024). "This study aimed to investigate the effect of VPA on the expression of the NKCC1, KCC2, and SLC5A8 co-transporters genes and the CDH1 and CDH2 genes in adult glioblastoma U87 MG (female) and T98G (male) cells." (PMID 39061990, 2024). "The expression of SLC12A2, SLC12A5, and CDH2 in adult glioblastoma U87 MG and T98G control cells differs significantly." (PMID 39061990, 2024). "In contrast, a negative strong significant Spearman correlation (R=-0.69, p = 0.0014) was observed for glioblastoma spheroids, indicating that CHI3L1 inhibition resulted in a reduction in CDH2 mRNA levels." (PMID 39607670, 2025). "In this context, using glioblastoma models, P2X7 activation has been related to the acquisition of EMT markers in mRNA (CDH2, SNAIL, Zeb1) and proteins (N-cadherin, ZEB1, vimentin, and TWIST), as well as the promotion of spheroid formation." (PMID 37966629, 2025). "Background/Objectives: The study aimed to determine the expression of carcinogenesis-related genes, such as SLC12A2, SLC12A5, CDH1, CDH2, EZH2, and GFAP, in primary glioblastoma (WHO Grade IV; IDH-wild-type) cells from three adult women: GBM5-1, GBM5-2F, and GBM5-3F." (PMID 41012498, 2025). "Then, we examined NOTCH1, CDH2 and SNAI1 three-gene signature in the Glioblastoma Multiforme (GBM) cohort (TCGA, Provisional, n = 577) and demonstrated its association with decreases in DFS (P < 0.05)." (PMID 30170559, 2018).
osteosarcoma (65 papers, 2013 to 2025). A usually aggressive malignant bone-forming mesenchymal neoplasm, predominantly affecting adolescents and young adults. "miR-194 directly inhibits the expression of CDH2 to reduce the proliferation and migration of osteosarcoma cells and promote cell apoptosis." (PMID 34127010, 2021). "In human osteosarcoma cell lines, miR-194 reduces cell proliferation, migration and promotes apoptosis by direct inhibition of CDH2 expression." (PMID 32284739, 2020). "In osteosarcoma, overexpression of miR-194 inhibits tumor growth and metastatic potential via the regulation of CDH2 and IGF1R." (PMID 26909612, 2016). "Overexpression of miR-194 inhibited tumor growth and metastasis of osteosarcoma probably by downregulating CDH2 and IGF1R. miR-194 may prove to be a promising therapeutic agent for osteosarcoma." (PMID 25096247, 2014). "In addition, miR-194 specifically downregulated the expression of IGF1R and CDH2. miR-194 gene therapy may prove to be a promising therapy for tumorsuppression in osteosarcoma." (PMID 25096247, 2014). "Using real-time quantitative PCR, we evaluated the expression of miR-194 and two miR-194 target genes, CDH2 and IGF1R in osteosarcoma samples from 107 patients and 99 formalin- or paraformalin-fixed paraffin-embedded tissues." (PMID 25096247, 2014). "Since our present findings associate cytoplasmic p27 localization with the metastatic potential of osteosarcoma cells, we evaluated the mRNA levels of the set of metastatic markers, VIM, SNA2, CDH2, CTNNB1 and STMN1 following XPO1 inhibition and AZD1775 exposure, by RT-qPCR." (PMID 30992462, 2019).
cervical carcinoma (60 papers, 2011 to 2025). A carcinoma arising from either the exocervical squamous epithelium or the endocervical glandular epithelium. "Various genes, namely GLS, CD36, WNT5a, HRAS, DDB2, PIK3R2, and CDH2 were found to be differentially highly expressed in primary cervical cancer samples of patients who developed distant recurrence." (PMID 35087740, 2021). "Among the eight identified EMT hub genes, CDH2 (N-cadherin) demonstrated a significant association with overall survival, while FN1 (fibronectin) was notably linked to disease-free survival, underscoring their prognostic value in cervical cancer." (PMID 41266827, 2025). "To investigate whether the direct interaction between miR-9-5p and TWIST1 can (partly) explain the different role of miR-9-5p in cervical SCC and AC, we analyzed expression of CDH1 and CDH2 in cervical cancer cells." (PMID 31888045, 2019). "Among eight EMT hub genes; CDH2 (N-cadherin) showed a significant association with overall survival (p = 0.0017, HR = 2.1), and FN1 (fibronectin) was notably linked with disease-free survival (p = 0.043, HR = 1.8), indicating their prognostic importance in cervical cancer." (PMID 41266827, 2025). "High CDH2 expression in cervical cancer cells coincided with low levels of miR-9-5p and high levels of TWIST1, suggesting a potential indirect effect of miR-9-5p on CDH2 via TWIST1." (PMID 31888045, 2019). "Namely, GLS, CD36, WNT5a, HRAS, DDB2, PIK3R2, and CDH2 were significantly DE between cervical cancer without recurrence and cervical cancer with distant recurrence." (PMID 35087740, 2021).
lung adenocarcinoma (48 papers, 2012 to 2025). A carcinoma that arises from the lung and is characterized by the presence of malignant glandular epithelial cells. "This study revealed that ADAM9 activates CDH2 through the release of miR-218 inhibition on CDH2 in lung adenocarcinoma." (PMID 24705471, 2014). "The regulation of CDH2 by miR-218-5p has been also reported in lung adenocarcinoma." (PMID 35628654, 2022). "Similarly, the RNA and protein levels of CDH2 were more abundant in another lung adenocarcinoma cell line, H1299, compared with A549 cells." (PMID 24705471, 2014). "We further demonstrated that ADAM9 could inhibit the expression of miR-218 and its precursor pri-miR-218-1 and could, in turn, up-regulate the expression of CDH2 to increase the mobility of lung adenocarcinoma cells." (PMID 24705471, 2014). "Furthermore, we over-expressed miR-218 in another lung adenocarcinoma cell line, H1299, and we found that CDH2 was also down-regulated both at the RNA and protein levels." (PMID 24705471, 2014). "Expression of TWIST1, mesenchymal (CDH2, VIM, SNAI1, ZEB1) and epithelial (CDH1, JUP) markers in lung adenocarcinoma cell lines." (PMID 22272264, 2012). "To understand whether the expression of ADAM9 and CDH2 were correlated with the malignancy of lung adenocarcinoma, we detected the endogenous expression levels of ADAM9 and CDH2 using real-time PCR and western blot analyses." (PMID 24705471, 2014).
liver cancer (34 papers, 2012 to 2025). An epithelial or non-epithelial malignant neoplasm that arises from the liver. "In in vitro models of liver cancer cell lines, the downregulation of miR-129-3p was associated with a reduced expression of epithelial markers (Cadherin 1 [CDH1] and CTNNB1) and an increase in mesenchymal markers (Cadherin 2 [CDH2] and Vimentin [VIM]))." (PMID 39598228, 2024).
breast tumor (31 papers, 2008 to 2024). "The blockade of TIM-3 in breast tumor explants downregulated genes related to cancer pathways, including those associated with tumor cell proliferation/migration/invasion (WNT5A, LIF, XDH2, SNAI, CDH2, ADAMST12, PLAU, and CDK14)." (PMID 32616706, 2020). "The METABRIC database (1904 human breast tumors) consistently revealed a positive association of NME4 with epithelial markers CDH1 and KRT18 and a negative association with mesenchymal markers CDH2 and VIM as well as many EMT drivers like ZEB1, ZEB2, SNAI2, TWIST1, and TWIST2." (PMID 34674701, 2021).
non-small cell lung carcinoma (30 papers, 2003 to 2025). A group of at least three distinct histological types of lung cancer, including non-small cell squamous cell carcinoma, adenocarcinoma, and large cell carcinoma. "CDH2 was reported to be related to the epithelial-mesenchymal transition (EMT) in non-small-cell lung cancer." (PMID 28694563, 2017).
pulmonary fibrosis (27 papers, 2013 to 2025). Chronic progressive interstitial lung disorder characterized by the replacement of the lung tissue by connective tissue, leading to progressive dyspnea, respiratory failure, or right heart failure. "Previous study showed that CDH2 was involved in epithelial-mesenchymal transition (EMT) which contributes to pulmonary fibrosis." (PMID 34476240, 2021). "Increased expression of CDH2 in mesenchymal cells has been hypothesized to play a role in idiopathic pulmonary fibrosis." (PMID 24023788, 2013). "Within this intersection, three hub genes, CALD1, CDH2, and POSTN, were found to be dysregulated and potentially significant in the context of pulmonary fibrosis." (PMID 38370408, 2024). "CALD1, CDH2, and POSTN, identified as potential contributors to pulmonary fibrosis, present promising therapeutic targets for IPF patients." (PMID 38370408, 2024). "Upon discovering the elevated expression of CALD1, CDH2, and POSTN in pulmonary fibrosis, we designed two pairs of siRNA for each gene to effectively knockdown their expression in HLFs." (PMID 38370408, 2024). "In the pseudostratified monocultures of the HBECs we observed the TGF-β1–induced EMT program described in lung fibrosis leading to the enhancement of the expression of mesenchymal genes as ACTA2, CDH2 and EMT-related transcription factors SNAI1 and SNAIL2." (PMID 33711932, 2021). "Furthermore, knockdown of CALD1, CDH2, and POSTN led to a reduction in TGF-β1-induced fibrotic markers, suggesting their potential roles in the development of pulmonary fibrosis." (PMID 38370408, 2024).
thyroid cancer (27 papers, 2016 to 2025). "The majority of drug-resistant cells in Thyroid cancer (THCA) tend to exhibit an Epithelial mesenchymal transition (EMT) phenotype, and abnormal expression of the cell adhesion molecule Cadherin2 (CDH2) is a hallmark of EMT." (PMID 35756646, 2022). "CDH2 is commonly up-regulated in various human cancers, including thyroid cancer, and its overexpression can promote tumor cell invasion." (PMID 30414611, 2018).
endometrial cancer (26 papers, 2011 to 2025). Primary or metastatic malignant neoplasm involving the endometrium (mucous membrane that lines the endometrial cavity). "Thus, we investigated whether expression of SESN2 correlates with that of the EMT markers, including CDH1 (encoding E-cadherin) and CDH2 (encoding N-cadherin), in the same dataset of endometrial cancer patients." (PMID 32899752, 2020). "In addition, a positive correlation was found between the expression of NUCB2/NESF-1 and EMT-related genes such as desmoplakin (DSP), Integrin Subunit Alpha V (ITGAV), metalloproteinase 3 (MMP3), tetraspanin 13 ( TSPAN13), and Cadherin 2 (CDH2) in endometrial cancer cells." (PMID 34361082, 2021). "The transcriptional complex of TEAD4 and AP-1 controls cell migration and invasion by regulating its downstream targets such as CDH2 (Cadherin 2) and MACF1 (Microtubule Actin Crosslinking Factor 1) in endometrial cancer and other cancers." (PMID 35602596, 2022).
metastatic tumors (23 papers, 2012 to 2026). "This was corroborated with increased gene expression of EMT markers such as TGFβ1, CDH2 and Snail correlating with higher Gleason score and/or metastatic tumor colonies in sites other than the tumors in prostate." (PMID 31360736, 2019). "This further confirms that N-cadherin protein is partially uncoupled from CDH2 mRNA levels, and that low N-cadherin levels identify patients with recurrent, metastatic tumors." (PMID 36880595, 2023).
squamous cell carcinoma (22 papers, 2003 to 2025). A carcinoma arising from squamous epithelial cells. "Cadherin-2 (CDH2) expression was significantly elevated in tumor-derived endothelial cells derived from both ADC and squamous cell carcinoma (SCC)." (PMID 34511114, 2021). "Only 31 of 1820 identified proteins were differentially expressed between adenocarcinoma (ADC)- and squamous cell carcinoma (SCC)-derived TECs (TEC-A and TEC-S, respectively), and cadherin-2 (CDH2) was the most significantly upregulated protein in TEC-A samples." (PMID 30832661, 2019).
endometriosis (19 papers, 2014 to 2025). The growth of functional endometrial tissue in anatomic sites outside the uterine body. "There is also some evidence that in endometriosis lesions the loss of CDH2 expression may be associated with increased invasive capacity of endometrial epithelial cells." (PMID 34445100, 2021). "However, whether activation of CDH2 by LINC01133 is responsible for the loss of proliferation capacity and increased invasiveness of endometriosis epithelial cells needs to be tested." (PMID 34445100, 2021).
esophageal cancer (19 papers, 2016 to 2026). A primary or metastatic malignant neoplasm involving the esophagus. "The potential mechanism of these ARGs were diverse; for example, CDH2, also known as N‐cadherin, could confer anoikis resistance in esophageal carcinoma with high intracellular PKCK2 activity." (PMID 36507553, 2023). "Previous studies have reported miR-495-3p could target CDK1, cadherin 2, and HMGB1 to display its functional role in various cancers, and BUB1 was demonstrated as the direct target of miR-495-3p in esophageal carcinoma." (PMID 40420658, 2025).
oral cancer (19 papers, 2016 to 2025). "Increased CDH1 and reduced CDH2 and VIM levels support the beneficial effect of ELLB in inhibiting cell migration and EMT in oral cancer cells." (PMID 36761830, 2022). "It even reduced the phosphorylation of ERK1/2 and AKT1 with concomitant downregulation of cyclin D1 (CCND1), cadherin 2 (CDH2), and vimentin (VIM) and upregulation of cadherin 1 (CDH1) expression suggesting its anti-proliferative and anti-EMT effects in oral cancer." (PMID 36761830, 2022).